PAIP1 (poly(A) binding protein interacting protein 1)
Diseases named in the same sentence as PAIP1 in open-access papers:
PAIP1 is named in the same sentence as 23 diseases in open-access papers, as found by Europe PMC text mining. Sharing a sentence is not in itself a finding about the gene and the disease. The quoted sentences say what the papers report.
hepatocellular carcinoma (4 papers, 2022 to 2023). A malignant tumor that arises from hepatocytes. "In fact, a previous study reports that PAIP1 is also highly expressed in cancer issues of hepatocellular carcinoma, and is a potential prognostic marker of patients." (PMID 37101794, 2023). "As we known, our study firstly identified the genome-widely regulated targets of PAIP1 in liver cancer, which is different from previous study of PAIP1 in hepatocellular carcinoma." (PMID 37101794, 2023). "Therefore, two independent set of data suggest that PAIP1 is a prognostic marker of hepatocellular carcinoma." (PMID 37101794, 2023). "screened potential autoantibody-based markers for hepatocellular carcinoma (HCC) and found that the AUC of an immunodiagnostic model including 6 TAAbs (RAD23A, CAST, RUNX1T1, PAIP1, SARS, PRKCZ) were 0.835 and 0.788 in the training and validation sets, respectively." (PMID 37251926, 2023). "However, previous published study does not reveal how PAIP1 functions in hepatocellular carcinoma." (PMID 37101794, 2023).
cervical cancer (2 papers, 2022). A primary or metastatic malignant neoplasm involving the cervix. "The upregulation and functional role of PAIP1 in the progression of several cancers like pancreatic, gastric, and cervical cancers have been reported." (PMID 35041720, 2022).
liver cancer (2 papers, 2022 to 2023). An epithelial or non-epithelial malignant neoplasm that arises from the liver. "However, the roles and underlying molecular mechanism of PAIP1 in liver cancer is still unclear." (PMID 37101794, 2023). "However, the roles and underlying molecular mechanism of PAIP1 in liver cancer are still unclear." (PMID 37101794, 2023). "The results indicated that PAIP1 would be a regulator factor of transcription, which affect the expression of immune and inflammatory genes in liver cancer." (PMID 37101794, 2023). "Here, to further explore the roles and regulated targets of PAIP1, we knocked down PAIP1 in HepG2 cells that was isolated from liver cancer tissue." (PMID 37101794, 2023). "Then, we analyzed the correlation between expression of PAIP1 and eight immune and inflammatory response genes in liver cancer tissues from the TCGA." (PMID 37101794, 2023). "Our study provides important cues for further study on the regulatory mechanism of PAIP1 in liver cancer." (PMID 37101794, 2023). "Our study provides an important basis and data platform to further clarify the role of PAIP1 in mediating progress of liver cancer." (PMID 37101794, 2023). "In conclusion, this study demonstrated that PAIP1 was high expressed in liver cancer tissue, and PAIP1 knockdown inhibit cell viability and extensively regulate the expression of a number of genes in HepG2 cells." (PMID 37101794, 2023). "Our study showed that PAIP1 knockdown can inhibit cell viability of liver cancer, which is consistent with previous studies." (PMID 37101794, 2023). "Taken together, our results demonstrated that PAIP1 was not only a translation regulator, but also a transcription regulator in liver cancer." (PMID 37101794, 2023). "However, the genome-widely regulated targets and mechanism of PAIP1 in liver cancer is still unclear." (PMID 37101794, 2023). "PAIP1 has also been reported to be a marker of increased invasive potential of liver cancer." (PMID 37101794, 2023). "We speculated that PAIP1 may play a role as immune regulator and promote the immune evasion of liver cancer cell, which partially interpreted that high PAIP1expression had shorter overall survival." (PMID 37101794, 2023). "Therefore, this study provides important cues for further study on the regulatory mechanism of PAIP1 in liver cancer." (PMID 37101794, 2023). "Thus, exploring the molecular mechanisms that PAIP1 regulate the immune and inflammatory factors will be meaningful to immunotherapy of liver cancer in future work." (PMID 37101794, 2023). "Thus, our study provides important cues for further study on the regulatory mechanism of PAIP1 in liver cancer." (PMID 37101794, 2023). "To verify whether PAIP1 was overexpressed in liver cancer tissues, we detected the expression of PAIP1 in liver cancer." (PMID 37101794, 2023). "We analyzed the expression of PAIP1 in liver cancer sample of the TCGA and the Human Protein Atlas database, the results showed that the expression of PAIP1 was obviously up-regulated in liver cancer tissues compared to normal tissues at both transcript and protein level." (PMID 37101794, 2023). "In addition, the expression of PAIP1 was knocked-down in another liver cancer cell Huh7 by transfecting vector with same three different PAIP1 siRNAs (siPAIP1-1, siPAIP1-2, and siPAIP1-3)." (PMID 37101794, 2023). "Additionally, compared to early-stage (stage i) liver cancer, PAIP1 showed a relative higher expression in advanced liver cancer (stage iii)." (PMID 37101794, 2023). "What’s role of PAIP1 in chemotherapy of patients with liver cancer?" (PMID 36436074, 2022). "Thus, it will be desirable to explore how PAIP1 functions in liver cancer." (PMID 37101794, 2023). "Moreover, the expression of PAIP1 was correlated with the prognosis of patients with liver cancer." (PMID 37101794, 2023). "Moreover, PAIP1 could function as a regulatory factor of immune and inflammatory genes in liver cancer." (PMID 37101794, 2023).
liver cancer (continued). "PAIP1 are highly expressed in many types of cancer, inducing liver cancer." (PMID 37101794, 2023). "In addition, the data suggested that PAIP1 was an oncogene in liver cancer." (PMID 36436074, 2022). "Thus, PAIP1 might be a potential prognostic factor in liver cancer." (PMID 37101794, 2023). "Thus, PAIP1 may play a role as immune regulator in liver cancer." (PMID 37101794, 2023). "Here, cell viability and the gene expression profile of liver cancer line HepG2 transfected with PAIP1 siRNA was compared with cells transfected with non-targeting control siRNA." (PMID 37101794, 2023). "Thus, PAIP1 would positively regulated PTAFR and IL1R2 in both HepG2 cells and liver cancer tissues." (PMID 37101794, 2023). "The results showed that the expression of PAIP1 had a significant negative correlation (P < 0.05) with that of APOC3, CCL14, IL1RN, SERPINA3, and HAMP in liver cancer tissues." (PMID 37101794, 2023).
colorectal cancer (1 paper, 2023). A primary or metastatic malignant neoplasm that affects the colon or rectum. "Compared with the normal control group, at least two of the three gastrointestinal cancers including gastric cancer group, the esophageal cancer group, and the colorectal cancer group, were significantly elevated in terms of the levels of anti‐PAIP1 and anti‐SARS in sera." (PMID 36587394, 2023).
familial amyotrophic lateral sclerosis (1 paper, 2016). An instance of amyotrophic lateral sclerosis that is caused by an inherited modification of the individual's genome. "Moreover, PAIP1 was reported to be highly expressed in microglial cells of familial amyotrophic lateral sclerosis." (PMID 27314336, 2016).
gallbladder cancer (1 paper, 2023). "As for the biology function, PAIP1 are highly expressed in many types of cancer, inducing breast cancer, lung adenocarcinoma, pancreatic cancer, cervical cancer, and gastric cancer, human tongue squamous cell carcinoma and gallbladder cancer." (PMID 37101794, 2023). "PAIP1 promotes gallbladder cancer through regulating expression of PLK1." (PMID 37101794, 2023). "Recently, several studies report that PAIP1 could regulated expression of AKT/GSK-3 β signaling pathway genes in lung cancer, Ki67, Pcna, Bax/Bcl2 and caspase-3 in tongue squamous cell carcinoma, and PLK1 in gallbladder cancer, respectively." (PMID 37101794, 2023).
glioma (1 paper, 2021). A benign or malignant brain and spinal cord tumor that arises from glial cells (astrocytes, oligodendrocytes, ependymal cells). "Among them, ARHGAP11A, DRP2, HNRNPA3, KLF10, PAIP1, and RCN1 have not yet been studied in gliomas." (PMID 34434651, 2021).
head and neck cancer (1 paper, 2022). A primary or metastatic malignant neoplasm affecting the head and neck. "Concurrent with our hypothesis, we found that the genetic alterations seen in head and neck cancers were mostly amplifications with mutations and fusions and a strong correlation between PAIP1 copy numbers and mRNA levels." (PMID 35153296, 2022). "This led us to hypothesize that PAIP1 might undergo amplification in head and neck cancer." (PMID 35153296, 2022).
head and neck squamous cell carcinoma (1 paper, 2022). A squamous cell carcinoma that arises from any of the following anatomic sites: lip and oral cavity, nasal cavity, paranasal sinuses, pharynx, larynx, and salivary glands. "In public database, PAIP1 was frequently amplified and overexpressed in a variety of cancers including head and neck squamous cell carcinoma (HNSCC)." (PMID 35153296, 2022).
lung carcinoma (1 paper, 2023). "Mechanistically, PAIP1 inhibits lung cancer cell proliferation and epithelial-mesenchymal transition related metastasis by regulating AKT/GSK-3 β signaling pathway." (PMID 37101794, 2023).
meningioma (1 paper, 2017). A generally slow growing tumor attached to the dura mater. "The trends of gene expression profiles of candidates such as EFCAB2, EPS8L1, NOL3, PAIP1 and SNX1 showed elevated expression in meningiomas compared to controls, while CAMK2N1, CRYM and PRPSAP2 showed decreased expression levels in meningiomas compared to the controls." (PMID 28938569, 2017).
oral cancers (1 paper, 2022). "Here, we used the data available from Gene Expression Omnibus (GEO), The Cancer Genome Atlas (TCGA), and Clinical Proteomic Tumor Analysis Consortium (CPTAC) to analyze PAIP1 expression in oral cancer." (PMID 35153296, 2022). "Indeed, we found a similar trend in the PAIP1 mRNA and protein level overexpression in oral cancers when compared to healthy controls 11–13,15,19." (PMID 35153296, 2022).
tongue squamous cell carcinoma (1 paper, 2023). A squamous cell carcinoma that arises from the tongue. "PAIP1 knockdown could decrease the expression of Ki67 and Pcna, and increased Bax/Bcl2 index and caspase-3 expression in human tongue squamous cell carcinoma." (PMID 37101794, 2023).
urothelial bladder carcinoma (1 paper, 2023). "Interestingly, recurrent mutations in PAIP1 have also been found in urothelial bladder carcinoma patients, suggesting a complex role of PAIP1 during tumorigenesis." (PMID 37543696, 2023).
tumor (8 papers, 2020 to 2025). "We found that high PAIP1 expressions significantly correlated with gender, tumor size, LNM, and stage, exhibiting a high-risk ratio." (PMID 35153296, 2022). "Parallel observations in the circRNA combination cohort revealed sustained downregulation of key classical oncogenes (PIK3CA) and novel tumor-associated genes (ANXA2, KIF2A, NCAPG2, PAIP1)." (PMID 40426998, 2025). "The results demonstrated that PAIP1 had a higher expression in tumor than normal liver tissue, and patients with high PAIP1 expression in tumor had a poor overall survival rate." (PMID 37101794, 2023). "In this study, the gene expression profiles and clinical information of liver hepatocellular carcinoma samples from TCGA were downloaded to analyze the expression of PAIP1 in all the tumor and normal liver tissues." (PMID 37101794, 2023). "In conclusion, current findings suggest that PAIP1 expression increased the possibility of LNM and advanced tumor stage, additionally it was also positively associated with WPOI." (PMID 35153296, 2022). "Most notably, we found that CCND1 and CCND2 were significantly downregulated upon PAIP1 knockdown in SMMC-7721 xenograft tumor cells, suggesting that PAIP1 promotes CCND1, CCND2, and MDM2 expression in HCC cells." (PMID 36436074, 2022). "Then, we found that MDM2 was significantly downregulated upon PAIP1 knockdown in SMMC-7721 xenograft tumor cells, suggesting that PAIP1 promotes MDM2 expression in HCC cells." (PMID 36436074, 2022). "Bioinformatics analysis and immunoblotting on SMMC-7721 xenograft tumor cells revealed that PAIP1 knockdown dysregulates several cyclin D pathway proteins." (PMID 36436074, 2022). "PAIP1 (poly(A)‐binding protein‐interacting protein 1) was detected only in tumor tissue and overexpression of PAIP1 in vitro stimulates translation." (PMID 32536039, 2020). "This implied that PAIP1 and SARS may play a role in multiple tumors and may be tumor‐associated antigens instead of HCC‐specific associated antigens." (PMID 36587394, 2023). "Overall, these findings gave evidence that circ_0005576 could participate in CC tumor occurrence and development via the miR-1305/PAIP1 axis." (PMID 35378711, 2022). "In this regard, PAIP1 surprisingly behaves as a tumor suppressor." (PMID 36436074, 2022). "Circ_0005576 depletion suppressed tumor development in CC by regulating the miR-1305/PAIP1 axis, suggesting that circ_0005576 might be a potential biomarker for CC treatment." (PMID 35378711, 2022). "Interestingly, we also found that CDK6 was significantly upregulated upon PAIP1 knockdown in SMMC-7721 xenograft tumor cells, suggesting that PAIP1 negatively regulates CDK6 expression in HCC cells." (PMID 36436074, 2022). "To determine whether PAIP1 has a reliable predictive value for OSCC prognosis, we assessed its association with the histopathological parameters in different regions classified as ITM (inner tumor mass) and ITF (invasive tumor front)." (PMID 35153296, 2022). "To examine the involvement of PAIP1 in SRC phosphorylation, closely related to tumor invasion and metastasis, we performed western blot in PAIP1 knockdown cells." (PMID 35153296, 2022). "Although these findings suggest that PAIP1 plays a part in tumor progression and metastasis as a potential prognostic factor, the correlation between PAIP1 expression and OSCC metastasis has not yet been described." (PMID 35153296, 2022). "However, PAIP1 expression did not significantly correlate with the histological differentiation of tumor." (PMID 35153296, 2022). "Moreover, the overexpression of PAIP1 enhances VEGF expression and can promote tumor angiogenesis." (PMID 35041720, 2022). "Finally, as expected, the PAIP1 and pSRC correlation results were in good agreement with data accessed via proteomic data commons for PAIP1 and phosphorylated SRC peptide (LIEDNEyTAR) at the site tyrosine 419, for paired healthy and tumor samples (P- and R-values of 0.003 and 0.724, respectively)." (PMID 35153296, 2022).
cancer (7 papers, 2012 to 2023). A tumor composed of atypical neoplastic, often pleomorphic cells that invade other tissues. "Poly Adenylate Binding Protein Interacting protein 1 (PAIP1) plays a critical role in translation initiation and is associated with the several cancer types." (PMID 35153296, 2022). "Numerous studies have shown that PAIP1 was upregulated and was associated with the development of multifarious cancers." (PMID 35378711, 2022). "Based upon the TargetScan analysis and the significant dysregulation in the KEGG ‘focal adhesion’ and ‘pathways in cancer’ pathways, we identified the focal adhesion/cancer-associated cyclin D pathway as a putative target pathway of PAIP1 dysregulation in HCC cells." (PMID 36436074, 2022). "PAIP1 expression was also associated with a malignant histopathological determinant, cellular cohesive, and non-cohesive invasion, which might clarify the aggressive behavior of cancers 24,25." (PMID 35153296, 2022). "Previous studies reported that PAIP1 knockdown inhibit the cell viability in a variety of cancer cell lines." (PMID 37101794, 2023). "Knocking down PAIP1 in a variety of cancer cell lines can inhibit the proliferation and metastasis of cancer cells, and/or induce apoptosis and cell cycle arrest." (PMID 37101794, 2023). "In recent years several studies show that PAIP1 are highly expressed in different type of cancer and are potential prognostic biomarker." (PMID 37101794, 2023). "To scrutinize the genetic alteration and expression of PAIP1 in various cancers, we first performed in silico PAIP1 expression analyses." (PMID 35153296, 2022). "Recently, certain studies attempted to assess the correlation between PAIP1 expression and the prognostic value in different cancers." (PMID 35153296, 2022). "Results of these studies indicated that PAIP1 is a potential prognostic biomarker for cancer." (PMID 37101794, 2023). "The dysexpression of PAIP1 may lead to proliferation, metastasis, and development of cancer." (PMID 35041720, 2022). "To further evaluate the PAIP1 expression in HNSCC, we assessed differentially expressed genes in 45 healthy and 45 cancer samples from the GSE dataset 30784 and found different, significantly upregulated PAIP1 transcripts." (PMID 35153296, 2022). "Here, we identified PAIP1 as an oncogene in HCC cells and provided a basis for the potential application of PAIP1 in targeted–therapy of cancer." (PMID 36436074, 2022). "The 5p12 region harbors some important genes, for example GHR (growth hormone receptor), SEPPI, PAIP1, NNT and FGF10 that may be related to cancer (for complete list of genes in amplification regions)." (PMID 22363777, 2012).
gastrointestinal tumors (1 paper, 2023). "Moreover, all of them except anti‐PAIP1, anti‐SARS, and anti‐SF3R3 were specific for HCC detection among common gastrointestinal tumors." (PMID 36587394, 2023).
PAIP1 also shares sentences with these, for which no sentence is quoted: pancreatic cancer (2 papers); esophageal cancer (1); gastric cancer (1); insomnia (1); multiple sclerosis (1); oral squamous cell carcinoma (1).